MET (MET proto-oncogene, receptor tyrosine kinase)
Diseases named in the same sentence as MET in open-access papers (continued):
Sharing a sentence is not in itself a finding about the gene and the disease.
multinodular goiter (1 paper, 2015). Nodular goiter characterized by more than one discrete tissue mass. "Separate analysis of a subset of the multinodular goiter samples with more aggressive PTC subtypes revealed 2 - 4-fold upregulation in the levels of CHEK1, c-MET and TIMP1, and a 2-4-fold downregulation of BCL2, c-KIT, TG and PPARγ (lower part)." (PMID 25868389, 2015).
myeloid malignancies (1 paper, 2014). "Hence, it is unlikely that the very frequent activation of the HGF/Met axis observed in myeloid malignancies results from MET mutation." (PMID 25119536, 2014).
neuroendocrine carcinoma (1 paper, 2023). A malignant neuroendocrine neoplasm composed of cells containing secretory granules that stain positive for NSE and chromogranin. "In neuroendocrine cancer, both MET and EGFR mediated signaling are highly activated, which is responsible for the adversity of the disease." (PMID 38168280, 2023).
neuroepithelial tumors (1 paper, 2024). "We report a series of three cases of infant-type hemispheric glioma (IHG) involving three infants diagnosed with neuroepithelial tumors of the cerebral hemispheres harboring a novel, recurrent TRIM24::MET fusion." (PMID 38902810, 2024).
non-melanoma skin carcinoma (1 paper, 2024). "Studies in non-melanoma skin cancer (NMSC) have shown that increased LGALS7 mRNA and Gal-7 protein expression are associated with myeloid programs, elevated CXCL1 levels, and c-MET activation." (PMID 39664377, 2024).
oligodendroglial tumor (1 paper, 2020). Oligodendrogliomas are cerebral tumors that are differentiated from other gliomas on the basis of their unique genetic characteristics and better response to chemotherapy. "However, at the cellular level, MET expression in oligodendroglial tumors seems to be lacking, and earlier reports state that MET positive cells were very rarely recognized in oligodendroglioma." (PMID 33066121, 2020).
osteoporosis (1 paper, 2023). A condition of reduced bone mass, with decreased cortical thickness and a decrease in the number and size of the trabeculae of cancellous bone (but normal chemical composition), resulting in increased fracture incidence. "For example, hepatocyte growth factor receptor (HGFR), encoded by MET gene, was negatively associated with BMD (beta = −0.04, p = 3.9 × 10−5), Cabozantinib may be repurposed to treat osteoporosis as an inhibitor of HGFR which was supported by real-world observation." (PMID 37448626, 2023).
ovarian squamous cell carcinoma (1 paper, 2020). A usually high grade squamous cell carcinoma that arises from the ovary and is not associated with a germ cell tumor. "We herein report a recurrent case of ovarian squamous cell carcinoma with MET gene copy number variation." (PMID 32475345, 2020).
parasite (1 paper, 2022). "Thus, to analyse the impact of the parasite infection on c-MET activation on neutrophils and its effect on the disease, and to be closer to the physiological parasite dose inoculated during a sand fly blood meal, we infected mice with a low dose of parasites." (PMID 35041723, 2022).
pericardial effusion (1 paper, 2022). Fluid collection within the pericardial sac, usually due to inflammation. "Meanwhile, EGFR L858R and MET amplification remained a modest consistence (40–80%) between paired pericardial effusion-cfDNA and pericardial effusion-sDNA." (PMID 35646096, 2022). "Among the actionable alterations, MET amplification exhibited the highest population frequency, while EGFR E746_A750delELREA, EGFR T790M, EML4-ALK (exon 20: exon 20) fusion, and KRAS G12C displayed a 100% consistency between the tumor tissue and pericardial effusions." (PMID 35646096, 2022). "Moreover, we identified EGFR L861Q and MET amplification as two unique actionable alterations in pericardial effusion, suggesting that NGS sequencing on pericardial effusion could lead to identification of advanced NSCLC patients who are qualified for TKI based therapy." (PMID 35646096, 2022).
peritoneal cancers (1 paper, 2020). A peritoneum cancer that is located in the inside of the abdomen. "The HGF/c-MET pathway has been targeted in clinical studies in gastro-oesophageal, ovarian and primary peritoneal cancers, with largely negative results." (PMID 32203220, 2020).
pituitary tumor (1 paper, 2021). A benign or malignant neoplasm affecting the pituitary gland. "Notably, activation of N-terminal truncated isoforms for MET and FGFR4 has been previously reported before in human musculoskeletal and pituitary tumors." (PMID 33482911, 2021).
pneumonia (1 paper, 2021). An acute, acute and chronic, or chronic inflammation focally or diffusely affecting the lung parenchyma, caused by an infection in one or both of the lungs (by bacteria, viruses, fungi, or mycoplasma.). "Moreover, in EGFR/MET-driven tumor samples, there were also extensive areas of alveolar hyperplasia and pneumonia, with alveoli filled with macrophages and plasma cells surrounding the adenocarcinoma mass or within edematous areas in the tumor." (PMID 34298655, 2021).
primary liver carcinomas (1 paper, 2004). "In human c-MET, point mutations have been described in the tyrosine kinase domain, which may be associated with the development of primary liver carcinomas." (PMID 15566568, 2004).
prostatic intraepithelial neoplasia (1 paper, 2020). "Increased expression of MET and phosphorylation in proliferative inflammatory atrophy (PIA) and prostatic intraepithelial neoplasia (PIN), which are known precancerous findings, have been reported." (PMID 32290402, 2020).
rectal tumors (1 paper, 2025). "Among the markers assessed, CEA, EpCAM, and c-MET demonstrated significant overexpression in rectal tumors." (PMID 40563608, 2025). "Our finding of abundant expression of CEA, c-MET, and EpCAM in most rectal tumors corroborates previous large-scale studies." (PMID 40563608, 2025).
Rett syndrome (1 paper, 2021). A severe neurodevelopmental disorder affecting the central nervous system.
salivary gland tumors (1 paper, 2021). "On the other hand, to better understand the effect of this protein on the pathogenesis and invasion of salivary gland tumors, it is suggested that angiogenesis and other markers such as HGF and c-MET be investigated simultaneously with CD138." (PMID 31540870, 2021).
Salmonella Infections (1 paper, 2022). Infections with bacteria of the genus SALMONELLA. "For the G2 group, the main pathways were: Salmonella infection (NFKB1, TJP1, DYNC2H1), transcriptional misregulation in cancer (MET, MLLT1, NFKB1), and adherens junction (MET, TJP1)." (PMID 36012418, 2022).
sarcoidosis (1 paper, 2014). Sarcoidosis is a multisystemic disorder of unknown cause characterized by the formation of immune granulomas in involved organs. "There is evidence of interrelation between Epstein-Barr Virus (EBV) infection and MET proto-oncogene expression, and at date several infection agents have been suggested to have an implication as cause of Sarcoidosis." (PMID 24416311, 2014).
serous carcinoma (1 paper, 2016). "The expression level of c-MET was significantly higher in OCCC tissue compared with normal ovarian tissue or serous carcinoma tissue (both p < 0.001)." (PMID 27917934, 2016). "c-MET expression was significantly greater in OCCCs compared with serous carcinomas and normal ovarian tissues (p < 0.001)." (PMID 27917934, 2016). "c-MET expression was estimated in human ovarian tissues, including 16 normal ovarian, 47 serous carcinoma and 16 OCCC tissues." (PMID 27917934, 2016). "In this study, we found that c-MET expression was significantly higher in OCCC, compared with serous carcinoma or normal ovarian tissue." (PMID 27917934, 2016).
T-cell acute lymphoblastic leukemia (1 paper, 2022). Acute lymphoblastic leukemia of T-cell origin. "The HGF/c-MET signaling pathway is involved in the occurrence and progression of hematological tumors including T-cell acute lymphoblastic leukemias." (PMID 36407095, 2022).
Thrombocytosis (1 paper, 2025). Increased numbers of platelets in the peripheral blood.
thrombosis (1 paper, 2021). "Among them, F2, MMP9, CXCL12, and MET are also the seed nodes in the network cluster analysis and have been shown that they have a multi-dimensional connection with thrombosis." (PMID 34433871, 2021).
tonsillar carcinomas (1 paper, 2015). "Particularly HPV negative tonsillar carcinomas with HGF or MET over-expression where associated with a reduced survival." (PMID 25633809, 2015).
vaginal melanoma (1 paper, 2023). A primary malignant neoplasm of the vagina composed of malignant melanocytes. "In this study, we showed that combinations of selected MET and EGFR inhibitors, crizotinib, foretinib and lapatinib, respectively, act effectively in the two commercially available MM cell lines as well as MM cells isolated from patient's vaginal melanoma." (PMID 37679999, 2023).
tumor (2,837 papers, 1991 to 2026). "MET overexpression is associated with adverse pathological features, increased tumor aggressiveness, bone metastasis, lineage plasticity, and resistance to AR-targeted treatments." (PMID 42122259, 2026). "We demonstrated that the use of type II MET inhibitors can effectively target tumours with selected MET mutations." (PMID 40437874, 2025). "Serum levels of soluble HGF in PDAC patients are associated with disease progression, and high tumour expression of c-MET is associated with poor prognosis." (PMID 41561521, 2025). "MET, a well-known oncogene in various tumors, has been associated with tumor growth through alternative splicing." (PMID 39773744, 2025). "Our pathway analysis identified five genes with a greater than 50-fold increase in tumor tissues, facilitating the further development of diagnostic markers to identify patients susceptible to MET-targeting therapies." (PMID 40565031, 2025). "A repeat tumor biopsy was performed for genetic analysis, and we further explored the potential mechanisms underlying MET inhibitor resistance in this case." (PMID 41268440, 2025). "Both HER2 and c-MET are well-established druggable targets implicated in tumor progression, metastasis, and therapeutic resistance across multiple cancer types." (PMID 40430804, 2025). "Among these, MET exon 14 (METex14) skipping mutations lead to dysregulated MET signaling through impaired receptor degradation, driving tumor proliferation and survival." (PMID 41573491, 2025). "In HCC, c-MET is frequently overexpressed, promoting tumor growth and angiogenesis, and is associated with poor prognosis." (PMID 41268440, 2025). "The tumor microenvironment also plays a pivotal role; stromal fibroblasts and tumor-associated macrophages can secrete hepatocyte growth factor, activating c-MET signaling and reinforcing resistance phenotypes." (PMID 41302945, 2025). "The mutation and deletion of this gene prevent proper receptor degradation, causing sustained MET activation and promoting uncontrollable cell proliferation and tumor growth." (PMID 41189945, 2025). "Biomarker-driven strategies, such as the detection of MET amplification, mutation, or overexpression in tumor samples, are critical for selecting appropriate candidates for c-Met inhibitor therapy." (PMID 40547482, 2025). "This complementary mechanism—involving simultaneous inhibition of EGFR (by AFT) and MET (by HAD-B1)—likely underlies the enhanced tumor suppression observed with the combination therapy." (PMID 40430565, 2025). "All patients with NSCLC with these alterations in their tumours had progressed on at least one line of therapy, suggesting that the MET mutation was the likely cause of the acquired resistance to prior therapy." (PMID 40437874, 2025). "The detection of MET mutation in cfDNA raises questions about its potential role in tumor progression." (PMID 40386554, 2025). "Resistance mechanisms involve genetic mutations (e.g., MET exon 14 skipping mutations), epigenetic alterations, and tumor microenvironment adaptation changes, and new strategies are urgently needed to overcome these barriers." (PMID 41064450, 2025). "Tepotinib is a kinase inhibitor directed against MET (mesenchymal-epithelial transition factor), a receptor tyrosine kinase overexpressed or mutated in a variety of tumour types." (PMID 40793752, 2025). "The METG1090A mutation was identified by next‐generation sequencing in tumour biopsies collected from a patient with a MET fusion‐positive NSCLC that was progressing on crizotinib, while the METY1230S substitution was found in a treatment naïve RCC." (PMID 40437874, 2025). "The miR-34a is a key regulator of tumor suppression controlling the expression of several targets involved in the cell cycle (c-MYC, E2F, CDK4 and CDK6), apoptosis (BCL2 and SIRT1) and tumor-associated invasion (c-MET)." (PMID 40755967, 2025).
tumor (continued). "Here, we characterise MET mutations identified in patients’ tumours and assess responsiveness to type I and II TKIs." (PMID 40437874, 2025). "In the SAVANNAH study, MET-IHC 90 or higher (3+ staining in ≥90% tumor cells) or MET FISH10+ (GCN ≥ 10) were associated with the survival benefits of combining osimertinib and savolitinib (ORR = 49%, mPFS = 7.1 mo)." (PMID 40470164, 2025). "Cellular mesenchymal-to-epithelial transition factor (c-MET) has been implicated in promoting tumor progression, metastasis and angiogenesis, whereas its inhibition has shown survival benefits in a phase II clinical trial." (PMID 41233805, 2025). "MiR-34b, a tumor suppressor miRNA, plays a crucial role in regulating various genes involved in cellular processes, such as MET, MYC, and NOTCH1, which are implicated in brain injury." (PMID 39129166, 2025). "In recent years, clinical studies have revealed a strong association between aberrant activation of the MET signalling pathway and tumour drug resistance, underscoring MET as a promising therapeutic target in OS." (PMID 40599602, 2025). "Somatic mutations that influence the copy number of individual MET exons in processed mRNA have been described in other tumor types." (PMID 40564049, 2025). "Pathological studies have demonstrated that gene amplification of MET and receptor overexpression significantly promote cellular behaviors associated with tumor aggressiveness." (PMID 38999251, 2024). "Overexpression of either MET or RON is associated with worse patient prognosis in a variety of tumor types." (PMID 39062731, 2024). "The internalization of SHR-A1403 was facilitated by binding the antibody to c-MET, leading to subsequent lysosomal translocation and cytotoxicity of the released toxin, likely serving as the primary mechanisms underlying its anti-tumor effects." (PMID 39664377, 2024). "Since the tumour tissue was positive for MET exon 14 skipping mutation, we commenced treatment with tepotinib at 500 mg/day." (PMID 38919814, 2024). "NPS-1034 inhibits multiple receptor tyrosine kinases (RTKs) implicated in tumor growth, metastasis, and angiogenesis, with targets including MET and AXL." (PMID 39451232, 2024). "Several MET inhibitors have been developed that that demonstrate considerable anti-tumor efficacy, particularly in cases with MET exon 14 skipping mutations (METex14) or MET amplification." (PMID 39201787, 2024). "MET amplification in GC has been associated with more aggressive tumour phenotypes, advanced stages and shorter survival, as previously demonstrated by this and other collectives." (PMID 38748262, 2024). "The mechanistic difference in conjunction with the prevalent genetic aberrations such as activating BRAF mutations likely determines the response of tumor cells to MET inhibition." (PMID 38386085, 2024). "Specifically, HGF has the ability to attract neutrophils for anti-tumor activities, while MET serves as a tumor-associated antigen (TAA) in facilitating immune-mediated tumor destruction." (PMID 39201787, 2024). "MET mutations are viewed as drivers if functional data have demonstrated their ability to induce cell transformation and/or experimental tumour growth." (PMID 38652103, 2024). "The overexpression of either MET or RON has been associated with worse cancer patient prognosis in a variety of tumor types." (PMID 39062731, 2024). "The effectiveness of MET kinase inhibitors is often limited by resistance mechanisms such as mutations that bypass MET inhibition or tumor microenvironment factors that reduce inhibitor efficacy." (PMID 39598385, 2024). "Molecular profiling and next-generation sequencing of tumor samples has provided insight on cancer-associated MET variants." (PMID 39071407, 2024). "c-MET, a tyrosine kinase receptor on the cell surface, is implicated in tumor growth, spread, and resistance." (PMID 39592929, 2024).